Y_RNA (Y RNA )
Gene: Miscellaneous RNA gene on chromosome 1 (28,422,555 to 28,422,655, reverse strand). Ensembl gene ENSG00000206779.
Homologues: Orthologues: chimpanzee Y_RNA (100% identical), macaque Y_RNA (97% identical). Paralogues in human: Y_RNA (93% identical), RNY3 (92% identical), Y_RNA (91% identical), RNY3P1 (90% identical), Y_RNA (90% identical), RNY3P14 (89% identical), Y_RNA (89% identical), Y_RNA (88% identical), RNY3P16 (87% identical), Y_RNA (87% identical), RNY3P11 (86% identical), Y_RNA (86% identical), and 95 more.